VIM (vimentin)
Diseases named in the same sentence as VIM in open-access papers (continued):
Sharing a sentence is not in itself a finding about the gene and the disease.
tumor (continued). "We hypothesized that vimentin inhibition would reverse the high tumor-grade phenotype and decrease metastasis of Pbrm1-null PDAC in mice." (PMID 40454484, 2025). "Our study suggests that combining Aurora B inhibitors with vinblastine could be a potential therapeutic strategy for tumor cells with high levels of vimentin or cells undergoing EMT." (PMID 40795355, 2025). "Similarly, in 5-FU-exposed isolated HT-29 cells, all EMT-related genes, including TWIST1, SNAIL1, ZEB1, Vimentin, and N-cadherin, showed upregulation than parental cells, while the tumor and EMT suppressor protein E-cadherin experienced downregulation." (PMID 40251609, 2025). "In the tumor panel, αSMA and Vimentin emerged as the highest-ranked markers." (PMID 40763304, 2025). "Tumour-suppressor PTEN expression declines while vimentin levels peak late in the trajectory." (PMID 40382312, 2025). "Similarly, SCs-derived NGF activates TrkA/ERK/ELK1/ZEB1 signalling in colon cancer cells inducing the expression of mesenchymal markers such as vimentin, N-cadherin and Zeb1 and promoting tumour invasiveness and metastasis formation." (PMID 40037534, 2025). "The observed coexistence of both molecular subtypes and heterogeneity, which we have also observed for EpCAM and Vimentin, might explain the observed minor variations between tumor tissue and tumor organoids." (PMID 40296444, 2025). "Similarly, vimentin (modulates tumor migration and invasion) and Slug (regulates snail expression and estrogen signaling) expression were significantly downregulated in the hAME and D + E groups compared to control." (PMID 40537738, 2025). "Because vimentin, which is involved in tumor invasiveness, was expressed mainly in the pericancerous SCC tissue of this patient, an invasive phenotype of cancer tissue could not be excluded." (PMID 40746833, 2025). "Vimentin positivity suggests that the tumor is derived from myofibroblasts." (PMID 40034204, 2025). "Vimentin highlights the potential invasiveness and metastatic capabilities of the tumor while CA IX suggests a role for metabolic adaptations that may influence therapy responses." (PMID 39851801, 2025). "To assess whether CXCR2 is responsible for the differentiation of GFs into αSMA- or vimentin-expressing CAFs within tumors, we conducted immunofluorescence double staining of tumor tissues." (PMID 40490643, 2025). "Additionally, N‐cadherin, vimentin, and migratory capability were decreased in Gö6983 or Gö6976 pretreated WT platelet‐incubated tumor cells and increased in PMA‐pretreated 10aa‐/‐ platelet‐incubated tumor cells." (PMID 40491968, 2025). "In mesenchymal tissue from a control duck gradually variable immunolabelling of different mesenchymal cells was observed, so expression of vimentin may vary and could be below the detection level in the tumour tissue." (PMID 40217475, 2025). "Several CAF IHC biomarkers, particularly CD163, MMP-9, periostin, and vimentin, significantly associated with prognosis in CRC, could be proposed as surrogates for the phenotypical characterization of the tumor microenvironment." (PMID 41450913, 2025). "In agreement with previous findings, patients with positive nodal status had increased expression of vimentin in primary tumor cells, and these tumor cells were characterized by reduced expression of Ki67, suggesting a mesenchymal and potentially drug-resistant state in the tumor cells." (PMID 40155451, 2025). "Immunohistochemically, tumor cells diffusely express Vimentin." (PMID 40224183, 2025). "Expression of CK18 (epithelial marker) and vimentin (mesenchymal marker) is typically mutually exclusive; however, during tumor progression, cancer cells may simultaneously express both markers, signifying partial EMT." (PMID 41472776, 2025). "PMC_2 marker (ITGA2) and fibroblast marker (VIM), were also markedly reduced in all treated groups, indicating lower PMC_2 and fibroblast infiltration, and their synergistic effect in disrupting the tumor-promoting microenvironment." (PMID 40976783, 2025).
tumor (continued). "In addition, during the process of EMT in tumor cells, keratin expression would be suppressed and replaced by Vimentin expression." (PMID 40486881, 2025). "Immunohistochemistry demonstrated tumor positivity for vimentin, epithelial membrane antigen (EMA), progesterone receptor (PgR), and thyroid transcription factor-1 (TTF-1) and negativity for cytokeratin and B-cell lymphoma-2 (Bcl-2), with a Ki-67 proliferation index of <1%." (PMID 40265140, 2025). "Vimentin, on the other hand, is mainly found in mesenchymal tissues as well as sarcoma cells, and its expression in tumor tissues can serve as an important clue to determine whether the tumor originates from mesenchymal tissues or not." (PMID 40361513, 2025). "However, blocking AKT phosphorylation can down-regulate the expression of downstream GSK-3β and inhibit the expression of EMT-related genes such as Vimentin, Snail and β-catenin, thereby inhibiting tumor metastasis." (PMID 40265472, 2025). "Moreover, immunohistochemical (IHC) results showed that injecting migrasomes significantly increased Ki‐67 and vimentin expression and decreased E‐cadherin expression in tumor tissues." (PMID 40056029, 2025). "Vimentin was focally positive in the basal and basolateral portion of the tumor cells." (PMID 40989704, 2025). "Then, the collected tumor tissues were tested and verified by IHC experiments, and the results exhibited that after circ_0008126 overexpression, the levels of vimentin, ki-67, and PCNA proteins had been down-regulated, while the levels of APC and E-cadherin proteins had been upregulated." (PMID 39858034, 2025). "Vimentin the mesenchymal marker expressed during EMT and its expression is associated with enhanced migratory and invasive capabilities enabling the dislodging of CTCs from the primary tumor into the bloodstream." (PMID 40260304, 2025). "Immunohistochemistry played a pivotal role in differentiating UPS, as the tumor was negative for hepatocyte-specific markers (arginase-1 and hepatocyte) and positive for vimentin and P16, aligning with diagnostic criteria in the literature." (PMID 40842593, 2025). "Although the molecular mechanisms underlying this effect are not fully understood, one hypothesis posits that TM downregulation promotes tumor cell migration by increasing vimentin expression and decreasing E-cadherin expression." (PMID 40746927, 2025). "Immunohistochemistry primarily aids in excluding other lineages, with tumor cells typically showing strong vimentin expression and cytoplasmic CD68 positivity (a histiocyte marker), while consistently negative for other lineage-specific markers, making UPS a diagnosis of exclusion." (PMID 41194829, 2025). "In DFML, spindle and stellate tumor cells exhibit high expression of vimentin and CD34." (PMID 41458523, 2025). "Immunohistochemistry revealed that the tumour cells were positive for vimentin and SMA expression, focal expression of calponin and CD10, and weak expression of β-catenin, with no expression of CD117, DOG-1, desmin, caldesmon, HMB45, ALK, CD34, S-100, CK, or SOX10." (PMID 41357577, 2025). "Moreover, knocking down P4HA1 also reduced the increase in E‐cadherin expression and the decrease in Vimentin expression in tumor tissue." (PMID 41469036, 2025). "In addition, miR-664b-3p inhibitor promoted the migration and invasion of tumor cells, as well as N-cadherin and Vimentin, and reduced E-cadherin." (PMID 40369698, 2025). "The use of markers such as Ki-67, vimentin, inhibin-α, or anti-Müllerian hormone may help clarify whether multiple tumor types arise independently or share common oncogenic pathways." (PMID 41302195, 2025). "In addition, XLLXF reverses the EMT by increasing E-cadherin expression and decreasing the levels of Vimentin, Twist1, and VE-cadherin, thus preventing tumor cells from acquiring an endothelial-like phenotype." (PMID 41019994, 2025).
tumor (continued). "Moreover, the elevated expression level of vimentin in HCC patients is intensely correlated with poor tumor differentiation, vascular invasion, extrahepatic recurrence, and reduced disease-free survival post-surgery." (PMID 40319186, 2025). "Interestingly, CD44hi/CD24hi cells exhibited a mesenchymal-type morphology and expressed higher levels of vimentin, consistent with our finding that CD44/CD24 coexpression in tumor cells was associated with vimentin-positive tumors." (PMID 40647395, 2025). "By immunohistochemistry, tumor cells also expressed vimentin, and ETV4." (PMID 39442927, 2025). "Third, vimentin plays a role in angiogenesis and the tumor microenvironment." (PMID 40937216, 2025). "Immunohistochemically, the tumor cells exhibit expression of Vimentin, CKpan, and EMA." (PMID 41170461, 2025). "Additionally, the tumor cells coexpress vimentin and cytokeratin, indicating a mixture of epithelial and mesenchymal features." (PMID 40362280, 2025). "Similarly, clustering was unable to distinguish PanCK+/Vimentin+ cells from tumor cells, fibroblasts, or stromal cells." (PMID 39969434, 2025). "Thus, vimentin-positive tumor cell clusters show lower levels of CD70-expression indicating that the epithelial phenotype is more associated with checkpoint’s expression." (PMID 40205178, 2025). "However, unlike single agents including CTX both double and triple combinations decreased Ki67+, Vimentin+ proliferative tumor cells and F4/80+ TAMs." (PMID 40568104, 2025). "Combining EpCAM with cell-surface vimentin (CSV) in circulating tumor cell enrichment could also be a promising strategy to enhance the capture of heterogeneous CTC populations, while addressing the limitations of relying solely on EpCAM-based methods." (PMID 40076201, 2025). "Notably, changes in the expression of markers such as S100A10, C1q, NES, VIM, and C3 and their mechanisms of regulating reactivity have only been investigated in reactive astrocytes under non-tumor disease conditions." (PMID 40243478, 2025). "The enrichment of these pathways in WT EVs implies that extracellular vimentin might play a multifaceted role in modulating both cellular plasticity and the immune landscape within the tumor microenvironment." (PMID 40618999, 2025). "Furthermore, compared to single treatments, the combination of carboplatin and KHSRP knockdown further reduced KHSRP, HMGB1, N-cadherin, vimentin, and Ki67 levels, and increased E-cadherin levels in mouse tumor tissues." (PMID 41194272, 2025). "Indeed, we observed a decrease in primary tumor growth and, conversely, an increased collective invasion of E‐cadherin‐, ZEB1‐, and vimentin‐positive tumor budding and metastasis to the lungs." (PMID 40644310, 2025). "Epithelial malignant tumor cells typically express the epithelial marker EpCAM on their surface; however, they often undergo epithelial-mesenchymal transition (EMT), leading to the loss of EpCAM and the expression of mesenchymal markers such as vimentin." (PMID 40718490, 2025). "Notably, vimentin inhibition in KPCPb–/– PDAC cells reversed the tumor grade of PDAC from poorly differentiated to well differentiated, and the loss of vimentin expression was confirmed by IHC analysis." (PMID 40454484, 2025). "Another study showed that the vimentin protein is involved in the development of the invasive phenotype of tumor tissues and is expressed mainly in poorly differentiated PCa and bone metastasis tissues, whereas it is almost undetectable in well-differentiated or moderately differentiated PCa." (PMID 40746833, 2025). "Additionally, western blotting served to assess E-cadherin, Snail, and vimentin expressions in mouse tumor tissues." (PMID 40746892, 2025). "Consequently, EMT was induced in tumour cells and resulted in E-cadherin downregulation and N-cadherin and vimentin upregulation, which enhances the PNI process." (PMID 40037534, 2025).
tumor (continued). "For instance, elevated ROS levels in tumor cells activate NF-κB, which in turn stimulates the expression of the transcription factor Snail, downregulates epithelial cadherin (E-cadherin), and increases the expression of neurocalcin and vimentin." (PMID 40181979, 2025). "Moreover, IHC revealed significantly decreased Ki‐67 and vimentin expression and increased E‐cadherin expression in the tumor tissues of the sh‐TSPAN4+PBS group." (PMID 40056029, 2025). "Immunohistochemical staining of these tumors confirmed higher expression of the proliferation marker Ki-67 and mesenchymal markers N-cadherin and vimentin, alongside reduced levels of E-cadherin, suggesting increased tumor aggressiveness and enhanced EMT characteristics." (PMID 40713830, 2025). "Additionally, E-cadherin expression increased in melittin-treated tumor cells, while N-cadherin and Vimentin levels decreased." (PMID 39519238, 2024). "Similarly, vimentin serves as a marker protein for mesenchymal stromal cells and promotes tumor infiltration and cell migration." (PMID 38710918, 2024). "Another way to assess the invasive capacity of tumor cells is by measuring vimentin expression." (PMID 39409923, 2024). "By IHC, the tumor cells were positive for Napsin A, Vimentin, and CK7." (PMID 39469368, 2024). "Tumor cells in the 2 cases were positive for vimentin, HMB45, Melan-A, and S-100." (PMID 38335433, 2024). "Immunohistochemical staining of the xenograft tumor tissue showed that the expression of Ki67 and Vimentin in the CFPAC-1 SOX21-AS1 group was significantly increased compared with that in the CFPAC-1 NC group, whereas the expression of E-cadherin was decreased." (PMID 38817864, 2024). "The mesenchymal component of the tumor may exhibit immunoreactivity to markers such as vimentin, smooth muscle actin, α-1-antitrypsin, and desmin." (PMID 39737275, 2024). "The tumor cells were positive for immunohistochemistry markers desmin, MyoD1, and vimentin." (PMID 38500901, 2024). "Based on an investigation by Li and coworkers, vimentin accumulation at the leading edge of the tumor cells might be a prerequisite for beginning dynamic invasion." (PMID 38474751, 2024). "By IHC, the tumor cells were positive for Vimentin, TLE1, and CD10." (PMID 39469368, 2024). "Tumor budding seems to be a dynamic process in which the ‘hybrid’ EMT phenotype of buds with downregulation of epithelial (e.g. cytokeratin) and upregulation of mesenchymal (e.g. vimentin) molecules causes further invasion into tissue." (PMID 38983934, 2024). "Based on the exosomal ADAM17 levels in the serum of patients with tumors, exosomal ADAM17 expression was negatively correlated with VE-cadherin, p120, and E-cadherin levels at the tumor invasive front and positively correlated with the expression of tumor blood metastatic protein vimentin." (PMID 38413999, 2024). "The EMT process is crucial for tumor cells to acquire mobility, and it is induced by decreased expression of the epithelial-specific marker E-cadherin and increased expression of the mesenchymal markers N-cadherin and vimentin." (PMID 38715919, 2024). "In particular, tumour buds lack cell cohesion and exhibit a mesenchymal phenotype, often showing reduced expression of epithelial markers (e.g., E-cadherin) and increased expression of mesenchymal markers (e.g., vimentin), indicative of EMT." (PMID 39429322, 2024). "Additionally, overexpression of miR-200c is known to down-regulate vimentin, which is known to inhibit cell migration and invasion, as well as to reduce metastatic tumour cells; thus, it leads to reduced EMT." (PMID 38255297, 2024). "Vimentin is exclusively expressed in CAFs surrounding the collectively invading tumor cells." (PMID 38730588, 2024).
tumor (continued). "Lathyrol and cisplatin inhibit the proliferation of RCC xenografts, reduce the protein expression levels of AR, CYP17A1, SPHK2, PARP1, E-cadherin, and ZO-1 in tumor tissues (P < 0.05), and promote the protein expression levels of N-cadherin, β-catenin, vimentin and α-SMA (P < 0.05)." (PMID 38965120, 2024). "Moreover, immunohistochemistry stainings of the DUSP8 tumor-bearing tissues showed increased expression of cytokeratin while vimentin was downregulated." (PMID 38396293, 2024). "There may be increased VIM expression in metastatic tumour deposits in the omentum, possibly due to greater involvement of stromal cells supporting the tumour cell nests." (PMID 39682273, 2024). "E-cadherin and vimentin are two pivotal factors in regulating tumor cells migration and invasion." (PMID 38216781, 2024). "Markers such as N-cadherin, vimentin, and fibronectin rose in the transformed clones, implying that the combination of loss of RAB25 and H-RAS61L overexpression was driving immortal HMEC toward a mesenchymal-like, stem cell-enriched tumor." (PMID 38803515, 2024). "Vimentin has been proposed as a potential anti-tumor target for cancer therapy." (PMID 38383479, 2024). "Since they are repressors of e-cadherin and are associated with tumor progression and invasiveness, the NLGP mediated normalization of e-cadherin and vimentin can easily be related to these findings and strongly confirms the ability of this drug as a potential EMT repressor." (PMID 38585261, 2024). "Vimentin, E-cadherin, and N-cadherin are markers associated with EMT to indicate tumor development." (PMID 39225900, 2024). "Further analysis revealed higher expression of vimentin in epithelial cells from non-recurrent tumours than from recurrent tumours and an association between low vimentin expression and poor recurrence-free survival." (PMID 38749574, 2024). "In addition, NTN4 overexpression inhibited breast cancer cells proliferation, migration, invasion and tumour formation, as well as downregulation in N‐cadherin and vimentin expression." (PMID 38546656, 2024). "Additionally, Ki‐67 and IHC staining for E‐cadherin, N‐cadherin and Vimentin in xenograft tumours revealed that the suppression of LYRM2 in HCC cells inhibited both the cell proliferation and EMT." (PMID 39661026, 2024). "Briefly, flanking 5 μM serial sections were stained either with H&E for pathologist review to define regions of interest with viable tumor content or with monoclonal antibody-fluorescent dye conjugates of E-cadherin, vimentin, and β-catenin, along with 40,6-diamidino-2-phenylindole (DAPI)." (PMID 38010394, 2024). "Notably, miR-642a-3p knockdown upregulated SERPINE1 and E-cadherin protein levels while downregulating N-cadherin and vimentin protein levels, indicating an inhibitory effect on tumor infiltration and dissemination." (PMID 39544420, 2024). "E-cadherin, N-cadherin, and vimentin are also involved in tumor cell invasion processes." (PMID 38474751, 2024). "Notably, N-Cadherin, Snail, and Vimentin are increased in cancer cells and act as tumor markers 25-27." (PMID 39308677, 2024). "Additionally, the immunofluorescence experiments showed that the tumor cells with matrix glue added significantly upregulated Vimentin." (PMID 38987529, 2024). "In addition, this therapeutic combination also notably diminished tumor growth in pancreatic CSC xenograft models, largely via the suppression of EMT-associated proteins, such as Zeb-1, Twist2, and vimentin." (PMID 38254735, 2024).